PNMA8C (PNMA family member 8C)
Gene: Protein-coding gene on chromosome 19 (46,424,697 to 46,428,936, reverse strand). Ensembl gene ENSG00000277531.
Homologues: Orthologues: chimpanzee PNMA8C (99% identical), macaque PNMA8C (98% identical), mouse Pnma8c (74% identical), rat Pnma8c (73% identical). Paralogues in human: PNMA8A (36% identical), PNMA2 (30% identical), PNMA5 (30% identical), PNMA6A (29% identical), PNMA3 (29% identical), PNMA1 (28% identical), MOAP1 (26% identical), PNMA6E (25% identical), PNMA8B (25% identical), PNMA6F (25% identical), CCDC8 (15% identical), ZCCHC18 (7% identical), and 1 more.